PRODH2 (proline dehydrogenase 2)
Description:
Dehydrogenase that converts trans-4-L-hydroxyproline to delta-1-pyrroline-3-hydroxy-5-carboxylate (Hyp) using ubiquinone-10 as the terminal electron acceptor. Can also use proline as a substrate but with a very much lower efficiency. Does not react with other diastereomers of Hyp: trans-4-D-hydroxyproline and cis-4-L-hydroxyproline. Ubiquininone analogs such as menadione, duroquinone and ubiquinone-1 react more efficiently than oxygen as the terminal electron acceptor during catalysis.
Synonyms: HYPDH; HsPOX1
Tractability: PROTAC: its protein half-life has been measured.
Target class: Enzyme; Oxidoreductase
Gene: Protein-coding gene on chromosome 19 (35,799,975 to 35,813,299, reverse strand). Ensembl gene ENSG00000250799.
Subcellular location (Human Protein Atlas): Nucleoplasm; Cytosol
Pathways (Reactome):
Metabolism: Glyoxylate metabolism and glycine degradation; Proline catabolism
Gene Ontology:
Molecular function: oxidoreductase activity, acting on the CH-NH group of donors; proline dehydrogenase activity; FAD binding; oxidoreductase activity, acting on the CH-NH group of donors, quinone or similar compound as acceptor
Biological process: L-proline catabolic process; trans-4-hydroxy-L-proline catabolic process
Cellular component: mitochondrial inner membrane; mitochondrion
Genetic constraint (gnomAD): Loss-of-function variants: 50 observed, 53.39 expected, observed/expected ratio (o/e) 0.94, 90% interval 0.75 to 1.18. The upper end of that interval is the gene's LOEUF score, 1.18, which puts it in group 5 of 6, group 1 being the genes least tolerant of losing a copy. Missense variants: 597 observed, 601.96 expected, observed/expected ratio (o/e) 0.99, 90% interval 0.93 to 1.06. Synonymous variants: 249 observed, 256 expected, observed/expected ratio (o/e) 0.97, 90% interval 0.88 to 1.08.
Gene-disease validity (ClinGen):
ClinGen rates the evidence that PRODH2 causes each of these diseases.
hydroxyprolinemia (autosomal recessive): Limited.
Homologues: Orthologues: chimpanzee PRODH2 (99% identical), macaque PRODH2 (96% identical), pig PRODH2 (85% identical), dog PRODH2 (85% identical), mouse Prodh2 (80% identical), rat Prodh2 (80% identical), tropical clawed frog prodh2 (51% identical), zebrafish zgc:92040 (45% identical). Paralogues in human: PRODH (39% identical).
Diseases named in the same sentence as PRODH2 in open-access papers:
PRODH2 is named in the same sentence as 16 diseases in open-access papers, as found by Europe PMC text mining. Sharing a sentence is not in itself a finding about the gene and the disease. The quoted sentences say what the papers report.
primary hyperoxaluria (3 papers, 2019 to 2022). A hereditary disorder characterized by excessive oxalate production, leading to hyperoxaluria. "Further studies are thus needed to evaluate the inhibitory effect of 4-oxo-l-proline and its analogs on PRODH2 activity as this enzyme could have therapeutic value in primary hyperoxalurias." (PMID 35150746, 2022). "Interestingly, PRODH2 has been proposed as a molecular target for treating primary hyperoxaluria, and some CoQ analogs seem to stimulate PRODH2 activity." (PMID 33810539, 2021). "In addition, PRODH2 is reported as a molecular target for treating primary hyperoxaluria." (PMID 31057604, 2019).
schizophrenia (3 papers, 2010 to 2022). A major psychotic disorder characterized by abnormalities in the perception or expression of reality. "The researchers provide evidence for a contribution of the Profline dehydrogenase 2 (PRODH2)/DiGeorge syndrome critical region gene 6 (DGCR6) locus in 22q11-associated schizophrenia, in three independent samples." (PMID 35547101, 2022). "Examples include SUMF1, KDM5B and MXRA5 (Known-ASD genes), PRODH2 and KCTD21 (implicated in schizophrenia), as well as USP9X and SMS (implicated in intellectual disability)." (PMID 28720891, 2017). "Examples include PRODH2 and KCTD21 (implicated in schizophrenia), USP9X and SMS (implicated in intellectual disability), TRIM9 and KDM5B (known-ASD genes), and others such as AGL and MOGS (candidate genes involved in energy metabolism and immune responses, respectively)." (PMID 28720891, 2017).
pancreatic cancer (2 papers, 2017 to 2022). "Moreover, pancreatic cancer patients with low PRODH, P4HA and PYCR1 expression had longer survival times than cancer patients with higher expression; in contrast, patients with low PRODH2 expression had shorter survival times than those with high PRODH2 expression." (PMID 36088469, 2022).
breast cancer (1 paper, 2025). A primary or metastatic malignant neoplasm involving the breast. "Notably, PRODH2-mediated hydroxyproline metabolism was found to promote osteoclast differentiation, which enhanced collagen degradation and facilitated breast cancer bone metastasis in vivo." (PMID 41488002, 2025).
colon cancer (1 paper, 2013).
hepatoma (1 paper, 2023). "In Huh7.5 hepatoma cells, the expression of proteins synthesizing proline from P5C (PYCR1, PYCR2, PYCR3) prevails over proline-utilizing proteins (PRODH and PRODH2) and the coordinated action of PYCR3, PRODH, and PRODH2 proteins." (PMID 37189460, 2023).
cancer (5 papers, 2020 to 2025). A tumor composed of atypical neoplastic, often pleomorphic cells that invade other tissues. "The gain-of-function targets were identified, and it was shown that overexpression of the PRODH2 gene (coding for proline dehydrogenase 2) can improve killing of various cancer cells by CAR-T cells." (PMID 37189725, 2023). "Compared with that in normal tissues, the expression of PRODH and PRODH2 was decreased in various cancer tissues, while that of P4HA and PYCR1 was increased in various cancer tissues." (PMID 36088469, 2022). "Developing stimulators of PRODH2/OH-POX catalytic activity could induce ROS-dependent apoptosis in cancer cells." (PMID 40454316, 2025). "Subsequent knock-in or overexpression of PRODH2-the leading target, enhanced the killing effect and in vivo efficacy of CAR-T in many cancer models, probably due to the transcriptomics and metabonomics broadly reshaped in PRODH2 high expressioned CAR-T cells." (PMID 37427373, 2023). "Moreover, increase in Hyp degradation by PRODH2/OH-POX contributes to decrease in cellular level of Hyp, eliminating highly energetic amino acid which supplements the energy needs of cancer cells." (PMID 40454316, 2025).
tumor (5 papers, 2023 to 2025). "They found that a targeted knock-in or the overexpression of PRODH2 encoding an enzyme in proline metabolism, which is an important metabolic process in T-cell effector activity, enhances the in vivo anti-tumor efficacy of CAR-T cells in multiple cancer models." (PMID 37569693, 2023). "Furthermore, PRODH2 supported tumor cell survival by upregulating the ferroptosis inhibitor SLC7A11, and stimulated osteoclast differentiation through increasing the production of the metastasis-related cytokine IL-8." (PMID 41488002, 2025). "Hydroxyproline can be catabolized by the metabolic enzyme proline dehydrogenase 2 (PRODH2) and enter the TCA cycle, generating energy and biosynthetic precursors to fuel rapidly proliferating tumor cells." (PMID 41488002, 2025). "Meanwhile, the overexpression of PRODH2 in CAR-T cells enhances their cytotoxic ability in vitro and in vivo, restructures gene expression and metabolism, and improves their long-term anti-tumor activity." (PMID 37569693, 2023). "PRODH2 engineering greatly enhanced CAR-T cell metabolic function and anti-tumor immunity." (PMID 38918817, 2024). "T cell metabolism could be manipulated using genetic engineering, as PRODH2 overexpression can shift cells to an OXPHOS-based metabolism with more active mitochondria and an increased percentage of CD45RA+/CD62L− T cells post-tumor challenge." (PMID 38699288, 2024).
PRODH2 also shares sentences with these, for which no sentence is quoted: hydroxyprolinemia (2 papers); cervical cancer (1); endometrial cancer (1); esophageal cancer (1); glioblastoma (1); Intellectual disability (1); melanoma (1); metabolic disorder (1).